PIK3R1 (phosphoinositide-3-kinase regulatory subunit 1)
Diseases named in the same sentence as PIK3R1 in open-access papers (continued):
Sharing a sentence is not in itself a finding about the gene and the disease.
pilocytic astrocytoma (1 paper, 2020). Pilocytic astrocytoma is a rare subtype of low-grade glioma of the central nervous system characterized by a well circumscribed, often cystic, brain tumor with a discrete mural nodule and long, hair-like projections that extend from the neoplastic astrocytes. "Both of these tumors lacked the accompanying PIK3CA or PIK3R1 mutation that is characteristic of RGNT, and both had epigenetic profiles aligning with pilocytic astrocytoma rather than RGNT." (PMID 32859279, 2020). "Additionally, DNT and pilocytic astrocytoma are characterized by either kinase domain tandem duplication or hotspot missense mutations, occasionally with accompanying NF1 or PTPN11 mutation, but lacking the accompanying PIK3CA or PIK3R1 mutation that characterizes RGNT." (PMID 32859279, 2020).
Respiratory tract infection (1 paper, 2025). An infection of the upper or lower respiratory tract. "In the patient harboring the pathogenic PIK3R1 variant, recurrent respiratory tract infections began at approximately 1 month of age, with splenomegaly and hepatomegaly developing at 10 years of age." (PMID 41583441, 2025).
retinal degeneration (1 paper, 2025). Degeneration of the retina. "In Pik3r1 knockout mouse models, altering Pik3r1 leads to an inability to recover phototransduction and increased susceptibility to retinal degeneration induced by stress." (PMID 40558514, 2025).
sebaceous carcinoma (1 paper, 2024).
sweet syndrome (1 paper, 2023). "We identified elevated IL-1 signaling in lesional Sweet syndrome skin caused by a PIK3R1 gain-of-function mutation specifically found in neutrophils." (PMID 36355435, 2023). "We describe the use of transcriptomics and genomic analysis to identify a gain-of-function PIK3R1 mutation in neutrophils from a patient with Sweet syndrome." (PMID 36355435, 2023).
Telangiectasia (1 paper, 2020). Telangiectasias refer to small dilated blood vessels located near the surface of the skin or mucous membranes, measuring between 0.5 and 1 millimeter in diameter. "Next-generation sequencing revealed mutations in the ataxia telangiectasia-mutated (ATM), SWI/SNF-related matrix-associated actin-dependent regulator of chromatin subfamily b-member 1 (SMARCB1), and phosphoinositide-3-kinase regulatory subunit 1 (PIK3R1) genes." (PMID 32537438, 2020).
thymoma (1 paper, 2013). A neoplasm arising from the epithelial cells of the thymus. "Since RPS6 is an effector of the AKT/mTOR pathway, we studied expression of its negative regulators PTEN and PIK3R1 but found them up-regulated only slightly (p < 10−3) in B3 thymomas." (PMID 24427739, 2013).
ulcerative colitis (1 paper, 2022). An inflammatory bowel disease involving the mucosal surface of the large intestine and rectum. "SRC, EGFR, AKT1, and PIK3R1 were the targets of highest potential, and the PI3K/Akt and MAPK pathways may be essential for the treatment of ulcerative colitis by bisdemethoxycurcumin." (PMID 36615264, 2022).
uterine tumor (1 paper, 2023).
viral pneumonia (1 paper, 2026). Inflammation of the lung parenchyma that is caused by a viral infection. "Through the construction of a comprehensive PPI network, we identified six core targets, including STAT3, AKT1, PIK3CA, PIK3R1, JUN, and MAPK1, which are likely central to the mechanism of action of DLQGD in viral pneumonia." (PMID 41601832, 2026).
tumor (247 papers, 2006 to 2026). "Introduction of GOF mutations in PIK3CD and PIK3R1 into T cells expressing either tumor-specific T cell receptors or various generations of CD19-directed CAR-T cells enhanced antigen-specific signaling, cytokine production, and tumor cell killing." (PMID 41280924, 2025). "The TCGA database shows that the loss of PIK3R1 copy number frequently occurs in various cancer types, which is consistent with the tumor suppressor role of p85α." (PMID 40657399, 2025). "Growth signaling aberrations, epigenetic dysregulation, and disruption of cell fate determination define the somatic mutational profile of our patient's tumor, which includes mutations in PIK3R1, KMT2D, and NOTCH1." (PMID 40124187, 2025). "PIK3R1 mutations can be detected via liquid biopsy, as 7.8% of mutations were found in tumor samples and 7.0% were found in cfDNA samples." (PMID 40564017, 2025). "Among tumors harboring PIK3R1 mutations, we observed the loss of the PIK3R1 allele in one tumor, amplification in two tumors, and the retainment of both alleles in another two tumors." (PMID 39858051, 2025). "For instance, PIK3R1 is known for its tumor-suppressing potential, which is associated with various cancers due to its mutations." (PMID 39872609, 2024). "In contrast, PIK3R1 (p85α regulatory subunit of PI3K) is a tumor-suppressor gene, and the protein p85α has a reduced capacity to restrain p110α when PIK3R1 is mutated, resulting in activation of PI3K-Akt-mTOR pathway." (PMID 39334689, 2024). "An increasing number of PIK3R1 has been identified as differentially expressed in many human cancers and associated with tumor progression and metastasis." (PMID 36688087, 2023). "The “MX-99” tumour also harboured somatic mutation in PIK3R1 (NM_181504: p.Y2fs), which is a regulatory subunit for PIK3CA with tumour-suppressor properties." (PMID 36522480, 2023). "It has been confirmed that tumor mutations in PIK3R1 were associated with enhanced PI3K signaling through weakening the ability of p85α to inhibit p110α6." (PMID 35395865, 2022). "In the past, a lot of research focused on characterize the functional consequence of PIK3R1 mutations and found that a subset of PIK3R1 mutations were considered functional and targeting these driver mutations has the potential to benefit tumor patients." (PMID 35395865, 2022). "PIK3R1 is reported to be differentially expressed in multiple cancers and is linked to tumor progression and metastasis." (PMID 34765599, 2021). "Among the genes that showed a negative correlation with SOCS1 and/or SOCS3, nine genes with high expression in tumor tissues predicted poor prognosis, whereas low expression of PIK3R1 was associated with bad prognosis." (PMID 32807134, 2020). "This was detected with an allele frequency approximately = 1.0, which suggested that this was a loss of function mutation followed by LOH, in accordance with PIK3R1 classification as a tumour suppressor gene." (PMID 32075097, 2020). "Similar observations were reported in hepatocellular carcinoma mouse models with liver-specific PIK3R1 deficiency wherein these mice had an increase in tumor development." (PMID 30755611, 2019). "PIK3R1 encodes the p85 regulatory subunit-α, which plays a tumor suppressor role, regulating and stabilizing the p110α catalytic subunit encoded by the oncogene PIK3CA." (PMID 31119098, 2019). "We found that LIFR expression in GBC tissues was closely associated with tumor size (P = 0.035), as was PIK3R1 (P = 0.040)." (PMID 31119098, 2019). "Supported by the notion of relatively frequent PIK3R1 mutations in PCa, this tumour suppressor role has also been propagated in this entity." (PMID 31828111, 2019).
tumor (continued). "In line with the proposed tumor-suppressive roles of p85α, PIK3R1 copy number loss is often detected in multiple tumor types including cancers of prostate, ovary, lung and breast." (PMID 30755611, 2019). "This tumor carries an in frame deletion in the PIK3R1 gene and a frameshift inactivating mutation of PTEN associated to its protein loss." (PMID 30038706, 2018). "An increasing number of PIK3R1 have been identified to be differentially expressed in many human cancers and implicated in tumor progression and metastasis." (PMID 30497511, 2018). "Hypermorphic mutations in PIK3CA and PIK3R1 genes, coding for the p110α and p85α proteins, are prevalent in numerous tumor types as verified by deep sequencing analyses in the frame of projects such as TCGA." (PMID 28143957, 2017). "We screened the entire coding sequence of PIK3R1 for mutations in 264 UC tumour tissues and 41 UC cell lines." (PMID 24367658, 2013). "Somatic mutations of PIK3R1 are observed in multiple tumor types, but the tumorigenic activity of these mutations has not been demonstrated in GBM." (PMID 23166678, 2012). "Based on current data sets, somatic mutations of PIK3R1 appear to be limited to a subset of tumor types." (PMID 23166678, 2012). "Although these mutations were detected less frequently in comparison to PTEN and PIK3CA mutations, the detection rate of PIK3R1 mutations was similar in both tumor and cfDNA samples (only a 0.8% difference), which implies that these mutations can be reliably detected when present in GBM patients." (PMID 40564017, 2025). "Cancers exhibiting PIK3R1 copy number loss may promote tumor development through distinct mechanisms that activate downstream signaling pathways." (PMID 40657399, 2025). "Notably, cfDNA mutations in PTEN were frequently associated with PIK3R1 mutations, and in our cohort, they correlated with a higher tumor grade (G3) and more than 50% of myometrial infiltration." (PMID 40227624, 2025). "Additionally, the tumor (estimated at 100% tumor content) was found to harbor an in-frame deletion in PIK3R1 p.Ile442_Thr454del and a recurrent hotspot missense variant in FGFR1 p.Lys656Glu." (PMID 39309743, 2024). "Indeed, the combined presence of PTEN and PIK3CA or PIK3R1 mutations are frequently observed suggesting that both loss of tumor suppressor and activation of oncogenes is required during tumor progression." (PMID 37591832, 2023). "Because in two cases a FGFR1 alteration in combination with PIK3CA or PIK3R1 mutation was present, the authors questioned whether such samples may represent a yet-to-be defined tumor class of RGNT outside of the stereotypic location in the fourth ventricle." (PMID 35018490, 2022). "A growing number of studies have shown that PIK3R1, which could regulate cancer cell proliferation, have been identified to play important roles in many human tumors carcinogenesis and implicated in tumor progression and metastasis." (PMID 35395865, 2022). "Mutations in genes such as AKT1, BCOR, and PIK3R1 were also observed and these genes may also contribute to tumor development." (PMID 31101826, 2019). "Of note, in addition to a mutation in the cancer driver Kras we detected two mutations in PI3K subunits Pik3r1 and Pik3ca and a deactivating stop-gain mutation of tumor suppressor Pten, which regulates PI3K by dephosphorylating the lipid signaling intermediate PIP3 to PIP2." (PMID 30262843, 2019). "Three out of 18 tumours with PIK3R1 functional mutations also had PTEN mutations." (PMID 27161491, 2016). "Interestingly, concurrent PI3K pathway mutations such as PIK3R1/PIK3R2 were recently identified as being involved in HNSCC tumor progression." (PMID 27528217, 2016). "One of these tumours had a mutation in the BH domain of PIK3R1 (W237_Y242del)." (PMID 24367658, 2013). "In summary, PIK3R1 mutations in primary GBM tumor specimens may define a subpopulation of patients who would benefit from treatment with MK2206 or other AKT inhibitors." (PMID 23166678, 2012).
tumor (continued). "Additionally, we assessed the anti-tumor activity of ARQ 092 in in vivo mouse models implanted with AN3CA cells (mutant PIK3R1, PTEN deficient, and activating mutation of FGFR2), KPL-4 cells (over-expression of HER2 and mutation in PIK3CA); and ZR-75-1 cells (ER positive, PTEN deficient)." (PMID 26469692, 2015). "We identified PIK3R1—a tumor suppressor down-regulating the PI3K pathway showing this two-hit scenario in both STAD and UCEC." (PMID 41415395, 2025). "CircRNAs can exert either anti-immunotherapeutic or anti-tumor effects by regulating the expression of PIK3R1 or binding to p85α." (PMID 40657399, 2025). "Key mutations in genes such as PTEN, PIK3R1, and KMT2C were significantly associated with a higher tumor grade and advanced stage disease, such as myometrial infiltration." (PMID 40227624, 2025). "There were also expression differences between the two primary tumours in ~ 50 insulin/glucose-related genes, such as SLC2A2, which encodes the GLUT2 glucose transporter and PIK3R1, involved in the metabolic actions of insulin." (PMID 40438247, 2025). "PIK3R1 functions as a tumor suppressor by stabilizing and inhibiting the catalytic activity of p110, and it directly binds to and enhances the activity of the PTEN lipid phosphatase." (PMID 40657399, 2025). "We summarize evidence indicating that PIK3R1 manifests characteristics consistent with a tumor suppressor gene." (PMID 40657399, 2025). "High-throughput base-editing screens have identified gain-of-function (GOF) mutations in genes such as PIK3CD, PIK3R1, and LCK, which enhance T-cell signaling, cytokine production, and tumor cell lysis." (PMID 41280924, 2025). "PIK3R1 encodes P85a, which stabilizes PTEN, and PTEN induces the dephosphorylation of PIP3 to PIP2, which plays a role in tumor suppression." (PMID 39949569, 2025). "Other shared hub proteins, including MAPK1, CDC42, and PIK3R1, are also involved in key signaling and regulatory pathways that support tumor progression." (PMID 41342186, 2025). "PIK3R1 encodes P85α, a crucial regulatory subunit of PI3K, and plays intricate roles in tumor progression and drug resistance." (PMID 40362183, 2025). "Tumor- and CRC-specific mutations were mostly synonymous or low-impact variants in genes including AKT1 (YCLO-2), BRAF (YCLO-2), FGFR3 (YCLO-7), and PIK3R1 (YCLO-7)." (PMID 40462147, 2025). "This requires glucose uptake and energy sources for normal cellular response to stress and tumor growth, syndrome development, vascular changes, and megalocephaly (e.g., PIK3R1; PIK3CA; PIK3CG; PIK3CD; PIK3CB; PIK3R3; PIK3R2; PIK3R5; PIK3R6)." (PMID 41010006, 2025). "The findings revealed that the suchilactone/kaempferol combination indeed activates murine spleen cells and exerts inhibitory effects on tumor cell activity through the targeting of PIK3R1." (PMID 38863309, 2024). "Our network pharmacology analysis suggests that Huangqi and Danggui modulate the expression of PIK3R1, thereby enhancing immunity and inhibiting tumor growth." (PMID 38863309, 2024). "The upregulated expression of miR-21 has been connected to poor clinical outcome, and recent functional studies have demonstrated that miR-21 promotes tumor cell proliferation and invasion by targeting tumor suppressors PIK3R1 and PTEN." (PMID 39594632, 2024). "Among these, jaranol emerges as the most significant component in the combined use of Danggui and Huangqi for enhancing immunity and inhibiting tumor growth by upregulating PIK3R1." (PMID 38863309, 2024). "The target PIK3R1 can be co‐regulated by multiple ingredients to initiate biological effects that are crucial for anti‐tumor immunity." (PMID 38863309, 2024).
tumor (continued). "The Pik3r1 protein product also has tumor suppressor potential since the downregulation of its levels favors the constitutive activation of downstream Akt signaling, which can induce carcinogenesis." (PMID 39684610, 2024). "We subsequently assessed the role of jaranol in anti‐tumor activity and immune system activation, with a focus on its interaction with the target PIK3R1." (PMID 38863309, 2024). "PIK3R1, a regulatory subunit of PI3K, is involved in controlling pathway activity, and its mutations can lead to hyperactivation, promoting tumor progression." (PMID 39850811, 2024). "IHC analysis and western blot analysis of tumor xenograft samples also showed that the levels of γH2AX and cleaved caspase-3 were obviously upregulated, whereas PIK3R1 and BRCA1 levels were decreased upon circPLPP4 inhibition." (PMID 38184597, 2024). "Specifically, the combinations of suchilactone with kaempferol and suchilactone with jaranol have been shown to enhance immune response and suppress tumor growth by targeting PIK3R1." (PMID 38863309, 2024). "Among others, CysGCA 5'-half and LysCTT 3'-tRF were upregulated in the tumor samples, and corresponded to decreased expression of PIK3R1, AKT1, and CPEB3." (PMID 39317063, 2024). "Based on network pharmacology analysis, PIK3R1 is the core target for the anti‐tumor immunity activity of combined Huangqi and Danggui." (PMID 38863309, 2024). "PIK3R1 is a potential protective target, which can negatively regulate the growth and invasion of tumor cells, and is closely related to the occurrence and development of tumor." (PMID 38533261, 2024). "PIK3R1, which controls cancer cell proliferation, is related to tumor growth and metastasis; PIK3R1 or PIK3R2 plays a role in the pathogenesis of distinct malignancies via common molecular processes." (PMID 36937843, 2023). "PIK3R1 (the code for p85α) was the most abundant isoform to be expressed broadly in normal tissues, functioning as a tumor suppressor." (PMID 37895906, 2023). "Although we identified the role of PIK3R1 in exacerbating NSCLC progression, the underlying mechanisms driving tumor progression need to be further elaborated." (PMID 36688087, 2023). "Research has shown that PIK3R1 is a potential target to evaluate cancer-specific molecular pathways and their correlation with tumor immune profile in cancer." (PMID 37430199, 2023). "For example, patient 31 is a 40-year-old man with GBM, and we detected three mutations— NF1:p.D1485lfs*8, PIK3R1:N/A, and PTEN:p.L23F— in his tumor tissue." (PMID 37920153, 2023). "PIK3R1 is the primary isoform regulating the tumor-suppressor gene phosphatidylinositol-4,5-bisphosphate 3-kinase (PI3K)." (PMID 36605494, 2023). "The six key-gene signature (ADRB2, DPYSL2, IL7R, LIMCH1, PIK3R1 and SOX2) has been shown to be associated with metastasis and progression of many tumor types through molecular experiments." (PMID 38057344, 2023). "Among the 1200 patients who underwent tumor exome analysis, we found a total of 141 patients (representing 11.75% of the screened population) with PIK3CA or PIK3R1 somatic mutation." (PMID 36934165, 2023). "On the one hand, elevated expression of FOXM1 promotes tumour cell proliferation and, on the other hand, FOXA1 inhibits tumour progression by suppression of PIK3R1 expression." (PMID 36688815, 2023). "In cell lines of HCC, the knockdown of PIK3R1 significantly reduced the expression of p-PI3K, p-AKT, and p-mTOR, which were closely associated with the growth and proliferation of tumor cells." (PMID 37240068, 2023). "At the molecular level, these tumor characteristic mutations included PTEN (88%), RPL22 (33%), KRAS (35%), PIK3CA (54%), PIK3R1 (40%), and ARID1A (37%) with high TMB levels (18 × 106 Muts/Mb) and certain TIL." (PMID 36578004, 2022). "Expression of PIK3R1 was found to decrease in most tumors from TCGA, which was in accordance with the assumption that PIK3R1 has tumor suppressive feature." (PMID 35395865, 2022).